DNMT3A (DNA methyltransferase 3 alpha)
Diseases named in the same sentence as DNMT3A in open-access papers (continued):
Sharing a sentence is not in itself a finding about the gene and the disease.
breast cancer (114 papers, 2004 to 2026). A primary or metastatic malignant neoplasm involving the breast. "RESULTS: DNMT3A SNP rs7605753 was significantly associated with increased breast cancer risk according to a recessive model (adjusted odds ratio [aOR]: 1.30; 95% confidence interval [CI]: 1.06, 1.59)." (PMID 41663987, 2026). "Haplotype analysis revealed that DNMT3A haplotype TACGA was associated with increased breast cancer odds compared to the referent haplotype CGCGA (aOR: 1.42; 95% CI: 1.13, 1.79)." (PMID 41663987, 2026). "A notable strength of this study is its gene-specific analysis, identifying mutations in ATM (OR = 3.97) and DNMT3A (OR = 1.33) as key contributors to breast cancer risk." (PMID 41382403, 2025). "Through published cancer-related datasets and clinical validation, we found that ADAMTS8 and DNMT3A expression negatively correlated in breast cancer, and both associated with patient prognosis." (PMID 40323963, 2025). "This study investigates the impact of genetic polymorphisms in DNA methyltransferases (DNMT1 and DNMT3A) on breast cancer pathomorphology and patient prognosis." (PMID 39597087, 2024). "Further functional validation in breast cancer cells is required to show the direct targeting of DNMT3A by hsa-miR-29c-5p and prove its causal role in determining luminal breast cancer phenotype." (PMID 33926515, 2021). "They down-regulated Maspin and SOX2 expression in SUM159 and MCF-7 breast cancer cell lines using a synthetic epigenetic construct of six ZF domain (6ZF) array linked to the DNMT3a catalytic domain (6ZF-DNMT3a)." (PMID 31597272, 2019). "To assess the clinical significance of MTA1/DNMT3a/IGFBP3 axis in breast cancer, we performed a two-way correlation involving low levels of DNMT3a and high levels of IGFBP3 associated with a poor distant metastasis-free survival." (PMID 28393842, 2017). "CONCLUSIONS: These findings suggest that genetic polymorphisms in DNMT3A may contribute to breast cancer susceptibility and that racial differences in haplotype distribution and associated risk merit further investigation." (PMID 41663987, 2026). "The identification of ATM and DNMT3A as high-impact mutations may hold particular relevance for early detection and risk stratification in breast cancer." (PMID 41382403, 2025). "DNMT3A encodes a DNA methyltransferase and modify DNA methylation which plays an important role in tumorigenesis and development in multiple cancers, including breast cancer." (PMID 32756009, 2020). "DNMT3A protein overexpression, detected with immunohistochemistry, has been previously linked to pejorative prognosis in solid cancers, such as retinoblastoma, breast carcinoma or gastroenteropancreatic neuroendocrine tumours." (PMID 29721185, 2018). "Similarly to the DNMT3A case, the regions differ slightly in their dominant mutation types; however, in all regions the majority of the mutations come from the same, endometrial and breast cancer, samples." (PMID 27150584, 2016). "METHODS: This nested case‒control study, conducted within the Arkansas Rural Community Health study (ARCH) cohort, examined the associations between polymorphisms in DNMT1, DNMT3A, and DNMT3B and breast cancer risk." (PMID 41663987, 2026). "Related cell experiments have shown that DNMT3A overexpression promotes breast cancer cell proliferation, migration, invasion, and apoptosis, whereas silencing DNMT3A has the opposite effect." (PMID 40323963, 2025). "Methylation-specific PCR (MSP) experiments confirmed that DNMT3A mediates ADAMTS8 promoter methylation in breast cancer." (PMID 40323963, 2025). "Further analysis of the ten most mutated CHIP genes revealed that mutations in DNMT3A and ATM were strongly linked to an elevated breast cancer risk." (PMID 40679991, 2025). "The risk of breast cancer associated with CHIP was predominantly driven by mutations in the gene ATM (OR [95% CI] = 3.97 [2.89–5.36], P = 2.02e-18), and DNMT3A (OR [95% CI] = 1.33 [1.03–1.66], P = 0.014)." (PMID 40679991, 2025).
breast cancer (continued). "CHIP is associated with an increased risk of breast cancer, particularly influenced by the ATM and DNMT3A genes." (PMID 40679991, 2025). "In our study, we found that mutations in DNMT3A and ATM were the most significant CHIP-associated mutations linked to breast cancer risk in both logistic and CoxPH models." (PMID 40679991, 2025). "As anticipated, the combined BSp + Ash diet significantly declined the expression of HDAC1 and DNMT3A in mammary tumors." (PMID 38802425, 2024). "Earlier, we have shown that the resistance of breast cancer cells to rapamycin or tamoxifen is related to decreased DNMT3A expression." (PMID 39624078, 2024). "In our mapping of biological pathways for breast cancer, DNMT3A, an enzyme responsible for de novo DNA methylation, is shown to be involved in miRNA expression." (PMID 38982523, 2024). "Collectively, our data highlight the significant role of the NR6A1/DNMT3A axis suppression in driving the progression of cross-resistance to hormonal and targeted chemotherapies in breast cancer cells." (PMID 39624078, 2024). "In breast cancer tissues and breast cancer cell lines, the expression of miR-101 is downregulated and the expression of DNMT3A is upregulated." (PMID 37298314, 2023). "In the nucleus of the breast cancer cell, Kindlin 2 forms a complex with DNMT3A, which occupies the promoter of miR-200b to promote cell invasion migration and stemness." (PMID 37298314, 2023). "In this study, we discovered that SND1 induces the transcription of DNA methyltransferase 3A (DNMT3A) in breast cancer cells." (PMID 37885030, 2023). "Accumulating evidence indicates that DNA hypomethylation resulting from DNMT3A activity is significantly related to chromatin remodelling and critically participates in the tumorigenesis and malignance of breast cancer." (PMID 37885030, 2023). "Breast cancer patients with advanced clinical stage disease or distant metastasis often have high expression of DNMT3A." (PMID 37885030, 2023). "Previous studies suggested that DNMT3A was overexpressed in various tumors, such as prostate cancer, breast cancer and PC, which was consistent with our findings." (PMID 37085288, 2023). "Among these prognosis-associated genes, four genes, AHCY, CBS, DNMT3A, and MTAP (p-value < 0.05), were common markers of poor prognosis for neuroblastoma and breast cancer." (PMID 36361596, 2022). "Stable silencing of SOX2 oncoprotein via overexpression of DNMT3A in mice retarded the tumorigenic phenotype of breast cancer cells." (PMID 35620052, 2022). "MiR-101 has been proven to inhibit cell migration and invasion by inhibiting the expression of DNMT3A and up-regulating the expression of E-cadherin in breast cancer cells." (PMID 36497343, 2022). "Li and others identified that circRNA circIQCH (hsa_circ_0,104,345) facilitated breast cancer progression via sponging miR-145 and increasing DNMT3A expression." (PMID 35620052, 2022). "It is necessary to mention that DNMT3A and DNMT3B have mutation and amplification in breast cancer patients." (PMID 35620052, 2022). "Breast cancer patients with advanced clinical stages often have high expression of DNMT3A and DNMT3B." (PMID 35620052, 2022). "In breast cancer, circIQCH sponges miR-145 to accelerate proliferation and migration process through upregulating DNMT3A." (PMID 36059626, 2022). "Kindlin 2, a focal adhesion protein to govern Wnt signaling pathway, can bind with DNMT3A and co-occupy the miR-200b promoter, leading to downregulation of miR-200b and promotion of invasion of breast cancer cells." (PMID 35620052, 2022). "DNMT3A induces promoter methylation and miR‐200b silencing to promote tumor progression in breast cancer." (PMID 36059626, 2022).
breast cancer (continued). "Emerging evidence has showed that the expression of DNMT3A and DNMT3B is linked to clinical features in breast cancer patients." (PMID 35620052, 2022). "Stilbenoid exposure resulted in SEMA 3A epigenetic activation via regulation of dynamic interactions of DNA with TF1C and DNMT3A in breast cancer cells." (PMID 35620052, 2022). "Increased DNMT transcript expression, including DNMT1, DNMT3a, and DNMT3b, in breast cancer tissues, suggests that DNMTs are involved in breast carcinogenesis." (PMID 35327559, 2022). "One study showed that high expression of DNMT3A was linked to promoter hypermethylation of ERα and BRCA1, and downregulation of ERα and BRCA1 in breast cancer patients." (PMID 35620052, 2022). "Multiple signaling pathways are validated to govern DNA methylation in breast cancer and some of these pathways are related to DNMT3a/DNMT3b." (PMID 35620052, 2022). "The DNMT1 and DNMT3A expression levels were significantly higher in breast cancer than in fibroadenoma samples." (PMID 33498667, 2021). "In breast cancer, all the isoforms of DNMT1, 3A, and 3B are overexpressed, and overexpression of DNMT3A was associated with poor prognosis in sporadic breast cancer." (PMID 34692471, 2021). "In breast cancer, miR-101 has been reported to act as a suppressor of cell proliferation by decreasing the level of DNA methyltransferase 3A (DNMT3A) and targeting proteasome maturation protein (POMP) and Stathmin 1 (Stmn1)." (PMID 34272359, 2021). "For instance, Flap endonuclease 1 was proved to interact with DNMT3A to repress miR-200a-5p expression mediated by methylation in breast cancer." (PMID 33087088, 2020). "Ralhan and co-workers showed that genistein is able to induce a significant decrease in the transcript levels of all the DNMTs including DNMT1, DNMT3a, and DNMT3b, in breast cancer." (PMID 32903500, 2020). "The results showed that circIQCH sponges miR-145 and promotes breast cancer progression by upregulating DNMT3A." (PMID 32756009, 2020). "We found that circIQCH sponges miR-145 and promotes breast cancer progression by upregulating DNMT3A and downregulating PTEN and BRCA1." (PMID 32756009, 2020). "DNMT3A is a DNA methyltransferase which plays an important role in tumorigenesis and metastasis by modifying DNA methylation in multiple cancers, including breast cancer." (PMID 32756009, 2020). "A further study showed that combination of sulforaphane and withaferin A, another natural compound, significantly causes down-regulation of overexpressed DNMT3a, DNMT3b, and HDAC1 and breast cancer cell death." (PMID 32903500, 2020). "The drug combination inhibited DNMT3a protein levels and increased expression of the tumor suppressor gene Cdkn2a/p16 in mammary tumors of HF offspring." (PMID 31889127, 2019). "The methylation/demethylation cycle was assessed in the breast cancer cells and tumorspheres through mRNA expression of DNMT3a, 3b, and TET1,2,3." (PMID 30915120, 2019). "The levels of DNMT-1, -3a, and -3b are generally upregulated in sporadic breast cancer and correlates with a poor prognosis; elevated DNMT1 level associates with lymph node metastasis, while DNMT3a and DNMT3b are associated with aggressive stages." (PMID 31426393, 2019). "For example, lower change in expression level of DNA methylating enzymes DNMT3A was observed in breast cancer cell lines 3 days after azacytidine treatment, as compared to colon and ovarian cancer cell lines." (PMID 31068808, 2019). "Consistent with human cell line data, Ets1 expression was negatively correlated with Dnmt3a and Dnmt3b in normal specimens, while Ets1 level is positively correlated with Apobec3c in human breast cancer specimens." (PMID 30467308, 2018).
breast cancer (continued). "In this study, miR‐200b expression in TNBC tissues was inhibited compared with other breast cancer subtypes, while DNMT3A and MYC expression were elevated significantly." (PMID 30324719, 2018). "In this study, we found that MYC proto‐oncogene, bHLH transcription factor (MYC) and DNA methyltransferase 3A (DNMT3A) were highly expressed in TNBC tissues compared with other breast cancer subtypes, while miR‐200b expression was inhibited significantly." (PMID 30324719, 2018). "Here, we found an inverse relationship between the levels of MTA1 and DNMT3a in human cancer and that high levels of MTA1 in combination of low DNMT3a status correlates well with poor survival of breast cancer patients." (PMID 28393842, 2017). "Mechanical compression induced miR-9 downregulation by DNMT3A-dependent promoter methylation in the MDA-MB-231 and BT-474 breast cancer cell lines and in cancer-associated fibroblasts." (PMID 28252641, 2017). "First, we examined the effect of overexpression or depletion of MTA1 on the status of DNMT3a in breast cancer cells." (PMID 28393842, 2017). "Like Oncomine datasets, we also found an inverse relationship between the status of MTA1 and DNMT3a mRNAs in 971 cases of breast cancers from the TCGA dataset analyzed using cBioPortal tools." (PMID 28393842, 2017). "Previous studies of epigenetic methylation-related proteins in breast cancer found that expression of DNMT1 and DNMT3a is higher in breast cancer than in benign lesions and the expression is related to breast cancer prognosis." (PMID 27071379, 2016). "DNMT3a and 3b have been confirmed as direct targets of miR-29c in lung carcinoma, breast cancer, and cutaneous melanoma." (PMID 26975503, 2016). "By contrast, the expression level of DNMT3a was the same in the drug-resistant breast cancer cell lines and the parental controls." (PMID 26980709, 2016). "The expression of several DNA methyl transferases (DNMT1, DNMT3a, and DNMT3b) has been found to be elevated in breast cancer tissue." (PMID 26694341, 2015). "In the case–control study presented herein, we correlated genetic polymorphisms in three genes, DNMT1, DNMT3A and DNMT3B, with clinical parameters to consider the risk of female Caucasians developing breast cancer." (PMID 23638630, 2013). "Consistent with previous findings that SFN decreased expression of DNMT1 and DNMT3a in breast cancer cells, SFN also decreased DNMTs expressions in our study." (PMID 22303414, 2011). "Another important discovery of this study is that SFN reduced DNMTs (DNMT1 and DNMT3a) activity in human breast cancer cells." (PMID 20625516, 2010). "We previously showed that, among the three DNA methyltransferases (DNMT1, DNMT3A and DNMT3B), only DNMT3B overexpression is associated with poor outcome in breast cancer." (PMID 15606925, 2004). "In addition, overexpression of vascular endothelial growth factor A (VEGFA) in breast cancer cells due to mechanical compression, was induced via DNA methyltransferase 3 alpha (DNMT3A)- dependent miR-9 reduction." (PMID 40171226, 2025). "De novo methylation, involving DNMT3A, plays an important role in cancer development; however, it remains unclear whether DNMT3A regulates the progressive expression of breast cancer by regulating ADAMTS8." (PMID 40323963, 2025). "Furthermore, our result indicated an expressional decline of epigenetic machinery HDAC1 and DNMT3A in mammary tumor tissue because of combinatorial treatment." (PMID 38802425, 2024). "We propose that coordinated suppression of NR6A1 and DNMT3A may be critical in sustaining the resistant phenotype and could potentially inform the selection of therapeutic regimens for breast cancer in the future." (PMID 39624078, 2024). "Metformin-activated AMPK increased DNMT3A activity in liver and breast cancer cells." (PMID 36959680, 2023). "In addition, higher expression of DNMT1 and DNMT3A was found in TNBC than in other breast cancer subtypes." (PMID 36982660, 2023).
breast cancer (continued). "Although the expressional regulation of its target genes such as DNMT1, DNMT3A and DNMT3B has been reported in breast cancer cells, one of its notable underlying mechanisms for the progression of malignancy is its binding with its target proteins and regulation of their activity." (PMID 38060527, 2023). "It suggests that a global increase in DNMT3a in a highly stressed breast cancer patient might result in the silencing or downregulation of NR3C1 and interfere with the regulation of the stress response, mediated by NR3C1." (PMID 36430579, 2022). "The expression of DNMT3A is higher in mammary tumors than in fibroadenoma." (PMID 35620052, 2022). "Overexpression of miR-101 caused the downregulation of DNMT3A and subsequent upregulation of E-cadherin expression in MDA-MB-231 cells, which is responsible for suppression of proliferation and migration capacity of breast cancer cells." (PMID 35620052, 2022). "Its expression in breast cancer was found negatively correlated with the mRNA and protein expression of the DNA methyltransferase DNMT3A, which can alter global DNA methylation levels and, amongst others, result in increased collagen type I (COL1A1) promoter activity, contributing to high MD." (PMID 35954468, 2022). "SFN may target the aberrant hypermethylation status by downregulating the expression of DNMT1 and DNMT3a in breast cancer cells." (PMID 36235389, 2022). "In addition, DNMT3A was discovered to be highly expressed in breast cancer with brain metastases in comparison with primary breast cancer patients." (PMID 35620052, 2022). "We also discuss the SNP and mutations of DNMT3A and DNMT3B in breast cancer." (PMID 35620052, 2022). "In breast cancer, miR-143 directly targets and regulates DNMT3A." (PMID 36090031, 2022). "By the analysis of transcriptomic data of more than 1500 cancer cell lines and patient samples, we show that the high expression of four genes from the methionine metabolism pathway (AHCY, CBS, DNMT3A, and MTAP) is associated with poor prognosis for breast cancer and neuroblastoma patients." (PMID 36361596, 2022). "Additionally, miR-194 was demonstrated to regulate DNMT3A expression pattern in drug resistant breast cancer cells and DNMT3A was shown to be the direct target of miR-194." (PMID 33604794, 2021). "In addition, ectopic HMGA2 expression also remodels chromatin in mammary tumor and breast cancer to a closed conformation at the Cdh1 locus by hypermethylation governed by HMGA2 interaction with DNA methyltransferases (DNMT3A)." (PMID 32365712, 2020). "For miR-200a, it was reported that miR-200a-5p 70 and miR-200a 71 could be methylated by Dnmt3a in the process of breast cancer proliferation." (PMID 32802189, 2020). "Conversely, tHIF-1α expression was barely detectable, whereas DNMT3a exhibited higher expression levels in ERα + breast cancer cell lines such as MCF-7 and T47D, suggesting that DNMT3a is most likely involved in methylation in the first exon of the HIF-1α gene in MCF-7 cells." (PMID 30940798, 2019). "DNMT3a exhibited an inverse expression pattern among the five breast cancer cell lines." (PMID 30940798, 2019). "To address which methyltransferases are responsible for DNA methylation at CpG sites and non-CpGs within the first exon of the HIF-1α gene, we detected the endogenous expression levels and patterns of DNMT3a and DNMT3b in various breast cancer cell lines by western blot." (PMID 30940798, 2019). "We found that there was an inverse correlation between the HIF-1α and DNMT3a expression levels in breast cancer cell lines and patient samples, suggesting that DNMT3a may be responsible for methylation of the HIF-1α promoter." (PMID 30940798, 2019). "By detecting DNMT1, DNMT3A, and DNMT3B mRNA levels, as well as DNMT3A protein levels in MAML1-overexpressing breast cancer cells, we confirmed that MAML1 could up-regulate DNMT3A expression." (PMID 31660998, 2019).